CD4 (CD4 molecule)
Diseases named in the same sentence as CD4 in open-access papers (continued):
Sharing a sentence is not in itself a finding about the gene and the disease.
latent infection (continued). "It is also suggested that latent infection is preferentially established in CD4+ T cells undergoing EMT." (PMID 33835029, 2021). "In contrast to EBNA-2 PRS-specific CD4+ T-cells during latent infection, perforin and granzyme B expression by NIL-specific CD4+ T-cells was in the absence of continued activation as shown by their lack of CD38 expression." (PMID 34882759, 2021). "It has been observed that quiescent and resting cell populations such as macrophages, resting CD4+ cells and memory T cell subsets are difficult to infect and biased towards unproductive or latent infections." (PMID 34962974, 2021). "Prestimulation of resting CD4 T cells with an anti-CXCR4 antibody has been shown to trigger cofilin activation that enhances HIV-1 latent infection of resting T cells." (PMID 34765923, 2021). "As expected based on previous studies, Tbet-expressing TH1 cells were the predominant effector CD4 T-cell subset generated during the latent infection." (PMID 35186781, 2021). "In this study we identify a population of tissue-specific memory CD4+ T cells expressing the IL-7 receptor-alpha chain that upon exposure to HIV preferentially supports latent infection by the virus." (PMID 32353080, 2020). "GaHV-2 establishes latent infection in CD4+ T lymphocytes, in which it integrates the viral genome into the telomeres of host chromosomes." (PMID 32967954, 2020). "Productive and latent infection significantly increased when resting CD4+ T cells were co-cultured with pDCs in the presence of anti-IFN antibodies compared to the isotype control (MFC 22, p = 0.03 and MFC 5, p = 0.03, respectively)." (PMID 32109259, 2020). "The ability of HIV to establish latent infection in CD4+ T cells is regarded as the main barrier to curing HIV, but despite two decades of research, it is unclear what mechanisms govern latent HIV infection in vivo." (PMID 33253324, 2020). "Adding pDCs to co-cultures of CD4+ T cells and mDCs resulted in a dose-dependent reduction of both productive and latent infection, indicating a pDC dominant negative effect." (PMID 32109259, 2020). "In conclusion, our study suggests that cell-intrinsic features of a specific subset of memory CD4+ T cells can bias them to preferentially support latent infection by HIV." (PMID 32353080, 2020). "The human T-cell lymphotropic virus type 1 (HTLV-1) is the etiological agent of adult T-cell leukemia/lymphoma (ATLL), a neoplasm of CD4+CD25+ T cells that occurs in 2–5% of infected individuals after decades of asymptomatic latent infection." (PMID 32645846, 2020). "To investigate if pDCs prevent latent infection via a dominant negative effect, we infected CD4+ T cells in the presence of mDCs and the pDCs were added back to the CD4+ T cell—mDC co-cultures at decreasing ratios of pDC to mDC (ranging from 1:1 to 1:1000)." (PMID 32109259, 2020). "The major barrier to a cure for HIV is the persistence of latent infection in long-lived and proliferating CD4+ T cells." (PMID 32109259, 2020). "CD8+ T cells are not sufficient to prevent lytic or persistent MHV-68 infection, however they contribute to CD4+ T cells which mainly control the latent infection." (PMID 31921215, 2019). "HIV-1 persists as a latent infection in CD4+ T cells that can be found in lymphoid tissues in infected individuals during ART." (PMID 30700598, 2019). "In this regard, extracellular Tat is known to favor the differentiation of naïve CD4+T cells towards the effector-memory phenotype, hence generating a pool of cells that are highly prone to latent infection." (PMID 31454973, 2019). "HIV-1 establishes latent infection in CD4+ memory T cells and persists indefinitely, even in individuals who are on HAART." (PMID 31487807, 2019). "CD8+ T cells are involved in resolving splenomegaly which is important in control of long-term latent infection, while the manifestation of splenomegaly is driven by CD4+ T cells depending on MHV-68-infected B-cells in the spleen." (PMID 31921215, 2019).
latent infection (continued). "IMPORTANCE HIV-1 persists as a latent infection in CD4+ T cells that can be found in lymphoid tissues in infected individuals during ART." (PMID 30700598, 2019). "A major reservoir of HIV latent infection resides in resting central memory CD4+ T cells (TCM) that escape clearance by current therapeutic regimens and will require novel strategies for elimination." (PMID 31142734, 2019). "Various mechanisms were proposed and demonstrated to establish latent infection in these deactivating CD4+ T cells." (PMID 30285810, 2018). "We also found that the proportions of EM Th1 cells are higher and those of CM Th1 cells are lower in active TB than during latent infection, which likely explains why the rapid cytokine response of CD4+ T cells is higher in active TB than in latent infection." (PMID 30283456, 2018). "Those who progressed from latent infection to active TB disease displayed T cell activation (indicated by elevated expression of HLA-DR on CD4 T cells) and a decrease in relative proportions of CD45RA-CCR7+ central memory CD4 and CD8 T cells." (PMID 30589870, 2018). "In this proof-of-concept study, diverse T-lymphocyte derived cell line models of HIV infection, including latent infection models, were preferred over primary CD4+ T cells in which production and selection of HT1-expressing cells would be challenging." (PMID 30395647, 2018). "The frequency and phenotype of T cells have been suggested to distinguish between active disease and latent infection as activated Mtb-specific CD4+ T cells are higher in active TB than LTBI." (PMID 29320502, 2018). "Overall, with this study, we confirmed that endothelial cells do promote HIV infection of resting CD4+ T cells, both productively and with latent infection, while keeping the T cells in a resting state." (PMID 30285810, 2018). "An overly intense IFNγ+CD4+ T cell response is the most important immunological parameter distinguishing the active disease from latent infection in these people." (PMID 28646367, 2017). "In summary, our study provides compelling evidence for the presence of polyfunctional, regulatory Th17, CD4 central memory T cells, specific for Mtb latency antigens to be a marker of latent infection." (PMID 28931830, 2017). "We tested the ability of R10015 to inhibit R5 and X4 latent infection of blood memory and resting CD4 T cells." (PMID 28381571, 2017). "In summary we have shown that HCMV establishes latent infection of huBLT mice resulting in the generation of both human CD4+ and CD8+ T-cell responses as well as HCMV neutralizing IgM and IgG neutralizing antibodies." (PMID 28428537, 2017). "Reactivation of latent infection into the active disease can be attributed to aggravated anti-Mtb IFNγ+CD4+ T cell responses." (PMID 28646367, 2017). "The ability of HIV to establish a long-lived latent infection within resting CD4+ T cells leads to persistence and episodic resupply of the virus in patients treated with antiretroviral therapy (ART), thereby preventing eradication of the disease." (PMID 28934369, 2017). "In conclusion, CCL19 enhances latent infection of resting CD4+ T-cells in a subset of donors at viral TCID50 titres of 0.5–2." (PMID 27383184, 2016). "Co-culture with mDC induced a higher frequency of latent infection in CD4+ T-cells compared to both unstimulated and CCL19-treated T-cells." (PMID 27383184, 2016). "Increasing the infectious titre of CXCR4-tropic HIV increased both productive and latent infection of resting CD4+ T-cells." (PMID 27383184, 2016). "Even with effective antiretroviral therapies, a cure for HIV remains elusive, due to persistent replication in lymphoid tissue sanctuaries and latent infection of resting CD4+ T cells." (PMID 27206407, 2016). "Next, we investigated the effect of various reactivation stimuli on the latent infection, in particular, of resting naïve CD4+ T cells maintained under HSP conditions." (PMID 27990142, 2016).
latent infection (continued). "We next compared the impact of virus inoculum on establishing latent infection of resting CD4+ T-cells in the presence of CCL19 versus another exogenous signal, co-culture with mDC." (PMID 27383184, 2016). "We have previously shown that chemokines that bind to chemokine receptors highly expressed on resting CD4+ T-cells can facilitate the establishment of latent infection in vitro via enhanced efficiency of nuclear localisation and integration." (PMID 27383184, 2016). "It has been argued that HIV-1 enter resting naïve cells less efficiently than memory cells, and that VSV-pseudotyped HIV cannot fuse or establish latent infection in unstimulated, resting CD4 T cells." (PMID 27990142, 2016). "Since very low levels of CCL19 (10–100 nM) are required for priming of resting CD4+ T cells for latent infection with HIV, we used 30 and 100 nM of CCL19 for subsequent infection and immunoblotting experiments, respectively." (PMID 27459960, 2016). "We next assessed the quality of the T cell response generated during latent infection by analyzing the activation state of CD4+ T-cells in infected lungs after 6 weeks of rifampicin and isoniazid treatment, and a further 3 weeks of infection reactivation." (PMID 27995986, 2016). "The persistence of HIV-1 in the face of potent antiretroviral drugs appears to be largely due to the ability of the virus to establish a state of latent infection in a long-lived population of resting memory CD4+ T cells." (PMID 26848681, 2016). "Using the CCL19 model of HIV latency, we found that in up to 50% of donors, CCL19 enhanced latent infection of resting CD4+ T-cells by CXCR4-tropic HIV in the presence of low dose IL-2." (PMID 27383184, 2016). "Most notably and in contrast with latent infection, our subjects with active TB disease had a predominance of CD4+ T cells secreting TNF alone which constituted 46% of the total cytokine response." (PMID 26339657, 2015). "Although, we did find that latent infection is more likely to occur in total resting lymphoid cell aggregates than in resting CD4+ T cells alone." (PMID 26067822, 2015). "Particularly important is the observation that CD14+ monocytes can induce latent infection in resting CD4+ T-cells." (PMID 26362311, 2015). "This study has established that multiple myeloid lineage APC subpopulations can facilitate latent infection in resting CD4+ T-cells." (PMID 26362311, 2015). "Combination antiretroviral therapy (cART) is able to control HIV-1 viral replication, however long-lived latent infection in resting memory CD4+ T-cells persist." (PMID 26362311, 2015). "We find that both resting and activated primary CD4+ T cells can support both productive and latent infection." (PMID 26067822, 2015). "Overall, our studies show that HIV infection can occur in both resting and activated CD4+ T cells, such that infection of resting cells more often results in latent infection and infection of activated cells more often results in productive infection." (PMID 26067822, 2015). "We tested the ability of APC subpopulations to induce both productive and latent infection in resting CD4+ T-cells when cultured alone or co-cultured with one of the seven sorted APC subpopulations." (PMID 26362311, 2015). "Conversely, untreated and CCL19-treated resting CD4+ T cells support more latent infection than productive infection." (PMID 26067822, 2015). "CD14+ monocytes represent DC and macrophage precursors in blood [Reviewed in 25], and were also tested for their ability to establish latent infection in resting CD4+ T-cells." (PMID 26362311, 2015). "Alternatively, latent infection can also occur following the direct infection of a resting CD4+ T-cell exposed to high viral titers and spinoculation, chemokines or co-culture with other cell types." (PMID 26362311, 2015). "Lastly, infecting untreated resting CD4+ T cells with a Vpx-containing virus significantly increased productive infection but only modestly increased latent infection." (PMID 26067822, 2015).
latent infection (continued). "Despite these differences, both dual-reporter viruses can detect latent infection events in activated CD4+ T cells early after the initial infection, and these latently infected cells can be reactivated by different stimuli." (PMID 26067822, 2015). "Based on the ratio of latently infected to productively infected cells, IL-7–treated resting CD4+ T cells and activated CD4+ T cells also support more productive infection than latent infection." (PMID 26067822, 2015). "In spite of prolonged and intensive treatment with combined antiretroviral therapy (cART), which efficiently suppresses plasma viremia, the integrated provirus of HIV-1 persists in resting memory CD4+ T cells as latent infection." (PMID 25625613, 2015). "Infection at day 4, when the CD4+ T cells were maximally activated, produced the highest levels of both productive and latent infection." (PMID 26067822, 2015). "As such, levels of productive infection increased significantly and were almost comparable to those of activated CD4+ T cells, whereas levels of latent infection were more than 2-fold greater than in resting untreated cells infected with HIV Duo-Fluo I alone." (PMID 26067822, 2015). "The level of PD-1 expression has been shown to influence the level of latent infection in CD4 T cells in patients on ART5." (PMID 25382623, 2014). "Results have shown that this drug can disrupt latent infection within a detectable proportion of the reservoir of latent resting CD4+ T cells." (PMID 24736215, 2014). "HIV-1 establishes latent infection in resting CD4+ T cells and findings indicate that latency can also be established in the cells of monocyte/macrophage lineage." (PMID 24759213, 2014). "In this study, we investigated the expression and function of CD244/2B4 on CD4+ T cells from active TB patients, latent infection individuals and healthy controls." (PMID 23638187, 2013). "These novel findings provide a potential pathway for the establishment and maintenance of latent infection in resting CD4+ T cells that recapitulates the likely events within lymphoid tissues in HIV-infected patients in vivo." (PMID 24339779, 2013). "A major reservoir of latent infection in vivo is within memory CD4+ T cells, although other cell types have been reported to harbor latent HIV-1, including cells of myeloid origin." (PMID 24156270, 2013). "This suggests that these isolates were able to enter within CD4+ T cells and were more inclined to produce latent infection than other isolates (where the levels of DNA and p24 were more consistent)." (PMID 23874501, 2013). "The expression of CD244 on antigen-responsive CD4+ T cells was elevated in retreatment TB patients compared with latent infection individuals (p = 0.0048) and new TB patients (p = 0.0038)." (PMID 23638187, 2013). "Mean fluorescent intensity (MFI) of CD244/2B4 expression on antigen-responsive CD4+ T cells was also significantly higher in retreatment active TB patients as compared with latent infection individuals (p = 0.0006) and new active TB patients (p = 0.0029)." (PMID 23638187, 2013). "In this study, we investigated the expression and function of CD244/2B4 on CD4+ T cells from active TB patients and latent infection individuals." (PMID 23638187, 2013). "Nor was it dependent on the amount of virus replication, because while only mDC were able to induce latent infection, similar levels of productive infection were observed in both the pDC and mDC co-cultured CD4+ T cells." (PMID 24339779, 2013). "In vivo, infected CD4+ T cells that have transitioned to a memory state form a primary reservoir of latent infection." (PMID 23874178, 2013). "The proportion of single positive Mtb-specific TNF-α-producing CD4+ T-cells was the strongest predictor of diagnosis of active disease versus latent infection." (PMID 24376464, 2013).
latent infection (continued). "Recently it has been reported that a TNF-alpha+ TB-specific CD4+response can be used to differentiate latent infection from active TB but the sensitivity was just 67%." (PMID 22666453, 2012). "This study focused on the role of chemokines—especially CCL19—in HIV-1 latent infection of resting T cells: Pre-treatment of resting CD4 T cells with the chemokines CCL19, CXCL9, CXCL10, and CCL20 led to a significant increase in integrated viral DNA." (PMID 22640593, 2012). "In fact, HIV-1 appears to utilize miRNA silencing to maintain a latent infection in resting CD4+ T cells, suggesting the miRNA profile of resting CD4+ T cells favors HIV-1 latency." (PMID 23251516, 2012). "Induction of actin dynamics through transient treatment with latrunculin A or a cofilin-activating peptide also enhanced HIV latent infection of CD4 T cells." (PMID 22640593, 2012). "We recently described that HIV latent infection can be established in vitro following incubation of resting CD4+ T-cells with chemokines that bind to CCR7." (PMID 21992606, 2011). "After a brief lytic phase in B lymphocytes (∼2 to 7 days post infection [dpi]), MDV establishes a life-long latent infection in CD4+ T lymphocytes." (PMID 21573129, 2011). "This is followed by spread and lytic cycling infection largely within CD4 TCRαβ T cell population, before development of latent infection and transfer of MDV into the feather follicle epithelium from where the infectious virus is shed." (PMID 21573129, 2011). "We have previously demonstrated that latent infection can be established in resting memory CD4+ T-cells in vitro following incubation with the chemokines CCL19 and CCL21 (ligands for CCR7), CXCL9 and CXCL10 (ligands for CXCR3) and CCL20 (ligand for CCR6)." (PMID 21992606, 2011). "In 2007, Lewin's group identified a novel mechanism of HIV latent infection of resting CD4 T cells, in which the CCR7 ligands, CCL19 and CCL21, were found to drastically increase the permissiveness of resting CD4 T cells to HIV infection." (PMID 20942936, 2010). "Using this system, we observed an absolute requirement of CXCR4 signaling for HIV-1 latent infection of resting CD4 T cells." (PMID 20041213, 2009). "We revisited the issue of chemokine coreceptor signaling and the role of cortical actin in HIV-1 latent infection of resting CD4 T cells, in which the virus can establish latency with a potential for productive replication upon T cell activation." (PMID 19851458, 2009). "Recently, we demonstrated a unique requirement for CXCR4 signaling in HIV latent infection of blood resting CD4 T cells." (PMID 19851458, 2009). "Recently, we examined the requirement for CXCR4 signaling in HIV-1 latent infection of human resting CD4 T cells using an in vitro system to mimic in vivo latent infection of resting T cells." (PMID 20041213, 2009). "With the recent demonstration of the signaling requirement for HIV latent infection of resting CD4 T cells, the issue of coreceptor signaling needs to be thoroughly revisited." (PMID 20041213, 2009). "In particular, signals transduced from the chemokine coreceptor CXCR4 have recently been shown to be essential for HIV-1 latent infection of resting CD4 T cells." (PMID 19851458, 2009). "In this study, we assessed the capacity of the preintegration reservoir to produce rescuable HIV-1-antigens from resting CD4+ T cells after polyclonal activation in an in vitro model of HIV-1 latent infection of resting CD4+ T lymphocytes." (PMID 17727722, 2007). "We first demonstrated in an in vitro HIV-1 latent infection model that HIV-1 production was rescued from infected resting CD4+ T lymphocytes after polyclonal activation." (PMID 17727722, 2007). "MDV establishes a latent infection, primarily in CD4+ T cells." (PMID 39840986, 2025). "Notably, the reduction in CD4+ and CD8+ T lymphocytes impairs the host’s capacity to mount effective cellular immune responses, increasing the risk of reactivation of latent infections, including TB." (PMID 40430808, 2025).